CCR6 (C-C motif chemokine receptor 6)
Diseases named in the same sentence as CCR6 in open-access papers (continued):
Sharing a sentence is not in itself a finding about the gene and the disease.
cancer (continued). "CCR6 inhibition in patients undergoing surgical treatment or clinical therapy has been proposed to be important to prevent liver metastasis of cancer, by a study of BALB/c mice." (PMID 30004409, 2018). "This demonstrates that CCR6 directs and drives the mechanisms of chemotaxis, commonly adopted by malignant cancers when metastasizing to the liver." (PMID 30004409, 2018). "Similar to tissue expression, CCR6 mRNA levels were significantly higher in cancer cell lines compared to normal esophageal epithelial cell lines (P < 0.001)." (PMID 29383156, 2017). "Higher expression of CCR6 in cancer cells compared with normal cells confirms the clinical significance of CCR6 in ESCC at cellular level." (PMID 29383156, 2017). "The chemokine CCL20 has been reported to promote cancer cell proliferation and migration through the chemokine receptor CCR6." (PMID 26248031, 2015). "As the total area of PyMT-driven hyperplastic outgrowth per gland was reduced by threefold in CCR6-null animals, we concluded that the effect of CCR6 on mammary tumorigenesis is manifested very early on in cancer development." (PMID 26047945, 2015). "Immunohistochemical analysis of NPC tissues revealed that MIP-3α and cystatin A were predominantly expressed in the cytoplasm of cells in the cancer nests, and CCR6 was expressed in the cell membrane." (PMID 26634210, 2015). "Our data suggest that activation of the CCL20/CCR6/IL-17 axis is also detectable in the histologically normal mucosa of smokers with cancer of the respiratory tract." (PMID 24497500, 2014). "Although CCR6 expression has been reported in several cancers and usually correlates with more aggressive disease, it's association with shorter RFS has never been demonstrated before." (PMID 21624121, 2011). "To confirm the role of CCL20 in autocrine stimulation of cancer cells from a different origin, we tested the expression of CCR6 in CCL20-secreting NB4, HL60, and HT-29 cells." (PMID 19340288, 2009). "CCR6 has been shown to be a target of certain cancer-derived factors, promoting Treg migration." (PMID 38283365, 2023). "Therefore, novel cancer treatment strategies using CCR6-expressing chimeric antigen receptor-T (CAR-T) cells have been designed." (PMID 37218898, 2023). "Studies have also indicated that CCR6+ cells may help to create a favorable environment for the development and growth of cancer cells, also increasing angiogenesis and migration of cancer cells." (PMID 37370832, 2023). "In the current study, CCR6 expression showed marked upregulation in many cancers, such as CM." (PMID 37182147, 2023). "Results of our study suggest that a loss of CCR6 expression and an increase in CCR7 expression may allow cancer cells to migrate to lymph nodes and lead to development of metastasis." (PMID 37316552, 2023). "CCL20/CCR6 axis works on cancer cells in autocrine and paracrine manners." (PMID 35864953, 2022). "Previous studies suggested that the co-localization of MIP-3α and CCR6 could promote cancer cell invasion." (PMID 35634309, 2022). "Thus, cancer cells can stimulate their own proliferation and migration in an autocrine manner, as well as cause angiogenesis via the binding of CCL20 to CCR6." (PMID 34659370, 2021). "Disruption of CCL20/CCR6 signaling would therefore be an alternative approach for cancer treatment." (PMID 32194362, 2020). "CCR6 activation may also increase the expression of VEGF in cancer cells, which contributes to angiogenesis." (PMID 33076281, 2020). "In addition, the CXCL12/CXCR4/CXCR7 and CCL20/CCR6 chemokine axes are known to promote migration and the invasiveness of cancer." (PMID 32775427, 2020). "CD44H, CD44v6 and CCR6 molecules may play a role in attachment of TMVs to cancer cells, while HER-2 associated with CD24 may be involved in promoting growth of cancer cells." (PMID 30925930, 2019).
cancer (continued). "Immunostaining of CCR6, E-cadherin and Vimentin were calculated as DAB-positive signals per mm2 of total membrane surface area and cytoplasm of tissue sections, the expression of CCR6 was significantly higher in cancer tissues compared with adjacent normal tissue." (PMID 29383156, 2017). "Previous research showed that overexpression of CCR6 could promote the invasiveness of cancer cells by interacting with other tumorigenic factors." (PMID 29383156, 2017). "The high expression of CCL20 may contribute to the selective recruitment of CCR6 positive cancer cells and metastases formation." (PMID 26626416, 2015). "CD44H, CD44v6 and CCR6 molecules may play a role in attachment of TMV to cancer cells, while HER-2 associated with CD24 be involved in promoting cancer cells growth." (PMID 26626416, 2015). "The liver may then selectively attract cells to attach and form micrometastases, perhaps by binding to putative integrin-like adhesion molecules that are possibly either induced or activated on cancer cells via CCL20/CCR6 interaction." (PMID 24979261, 2014). "It is speculated that CCR6-mediated chemotaxis may be a common mechanism of malignant tumor metastasis, suggesting that CCR6 signaling pathway suppression may prevent the risk of liver metastasis." (PMID 24743888, 2014). "Therefore, for the definitive confirmatory study, we grafted CMT93 CRC cancer cells into CCR6−/− mice." (PMID 21559338, 2011). "Up-regulation of CCR6 expression has been observed in various cancer entities." (PMID 20459729, 2010). "Here we show that, CCL20 promotes the growth and adhesion of CCR6-expressing cancer cell lines." (PMID 19340288, 2009). "The CCL20/CCR6 axis contributes to the activation of NF-kB and secretion of MMP-3, which promote cancer cell invasion and migration." (PMID 40150133, 2025). "Thus, the CCR6 antagonist currently under clinical trial (phase I) developed for anti-inflammation activity (NCT04388878) could be a feasible option for combined treatment with EGFRi for EGFRi-resistant cancers." (PMID 38551001, 2024). "A brief summary of the important genomic findings follows:In liver SM of CR cancer, the expression of VEGF, CXCR4, COX2 mRNA, TGF-α, and ISR1 was found to be significantly higher in SM compared to MM, while that of Cyclin E, CCR6 and FAK significantly lower." (PMID 37340186, 2023). "CCL20 was the ligand of CCR6 and reported to be accountable for recruiting CD4+ T cells to promote STAT3 activation to foster cancer stemness." (PMID 33514440, 2021). "While CCL14 and XCL1 have shown only good prognostic value, other chemokines such as CCL5, CCL20/CCR6, CCR7, CXCL1, CXCL8, and CXCL12/CXCR4 have consistently played the role of poor prognostic markers in different kinds of cancer." (PMID 31991604, 2020). "The CCR6/CCL20 axis thus demonstrates a vital role in determining the disease outcome of inflammatory disorders and cancer metastasis in multiple organ systems in the human body." (PMID 30004409, 2018). "CD26high T cells expressed Th1/Th17 chemokine receptors (CCR6, CXCR3, and CD161), whereas CD26neg T cells expressed CXCR3, confirming that cell subsets within these cultures are comparable between cancer patients and healthy individuals." (PMID 29213079, 2017). "Collectively, these findings indicate that circulating CCR6 and CXCR6-expressing MAIT cells can be easily attracted into the cancer tissues releasing the corresponding chemokines, such as CCL20 and CXCL16, respectively, in MAC patients." (PMID 27517754, 2016). "Chemokine receptor 6 (CCR6) and its ligand, CCL20, were highly expressed in a variety of human cancers." (PMID 24743888, 2014). "Both CMT93 cancer cells and macrophages produced a large amount of CCL20, the sole ligand of CCR6 in vitro and in vivo." (PMID 21559338, 2011).
cancer (continued). "Although the development of drugs modulating the CCL20/CCR6 axis is expected but currently not available, blocking the CCL20–CCR6 axis in combination with standard cancer therapies has shown promising results." (PMID 39985603, 2025). "CCR6 binds with its ligand CCL20, promoting cancer progression." (PMID 39273632, 2024). "At the single‐cell level in non‐responders, nearly all immuno‐suppressive/exhausted markers as PD‐1, CTLA4, and BTLA, along with CCR6, a receptor comprising CCR6/CCL20 axis and promoting cancer progression, elevated consistently in peripheral HLA‐DR+CD8+ T cells." (PMID 39467150, 2024). "Through CCR6, this chemokine may increase VEGF expression in cancer cells, or promote angiogenesis in ECs." (PMID 36835506, 2023). "Our results revealed an increased presence of CD8+ CCR6+ CCR5− CXCR3+, which can be correlated with the acquisition of an effector phenotype and further antitumor responses contributing to the immune system‘s action against cancer cells." (PMID 36551555, 2022). "Interestingly, low protein expression levels of CCR6 and CCR8 were found in cancer tissues and adjacent tissues." (PMID 32641093, 2020). "PDAC tumors have a subset of highly overexpressed (and highly expressed in terms of magnitude) chemokine receptors (CCR6, CCR7, CXCR3 and CXCR4) not expressed in PDAC cancer cells but likely associated with immune cells and their activation." (PMID 31765370, 2019). "CCR6 was expressed on a low proportion of normal mammary cells, but this proportion was greatly amplified in accordance with increasingly higher grades of MMTV-PyMT cancer including initial hyperplasia, early carcinoma and late carcinoma as indicated." (PMID 26047945, 2015). "Furthermore, our data suggest an in vivo role of the chemokine CCL20 in CXCR4 dependent and independent regulation of cancer growth and point to CCR6 and CCL20 as novel therapeutic targets in cancer." (PMID 19340288, 2009). "Furthermore, our data suggest a role of the chemokine CCL20 in CXCR4-dependent and independent regulation of cancer growth and point to CCR6 and CCL20 as novel therapeutic targets in cancer." (PMID 19340288, 2009). "Besides, whether the SIK1/PI3K/AKT and CCL20/CCR6 signaling pathways for miR-183-5p are specific in HCC and whether the axis has an effect on angiogenesis in other cancers remain questions that need to be explored." (PMID 40115013, 2025). "However, to our knowledge, no previous reports focused on macrophage expressing CCR6 in the cancer microenvironment." (PMID 34178651, 2021). "Even while CCR6 is not considered a typical checkpoint inhibitor, some evidence suggests that targeting CCR6 may enhance the efficacy of immune checkpoint inhibitors in treating certain types of cancer, including CRC." (PMID 37370832, 2023). "As TNF-α enhances CCR6 expression, CCR6+ cells interact with CCL20, facilitating migration in cancer cells but not affecting normal thyroid cells." (PMID 40150133, 2025). "Hence, the CCR6/CCL20 axis was found to be engaged in the proliferation and migration of cancer cells via autocrine or paracrine mechanisms, and it was suggested that disruption of the functions of this chemokine duo may offer a promising strategy to treat cancers in the lung." (PMID 30453514, 2018). "IL-1β did not regulate CCR6 or CCR7, two other CC chemokine receptors related to cancer metastasis, in either Tca8113 or Hep2 cells." (PMID 26176534, 2015). "The study highlighted the fact that the post-operative MIP-3α level may therefore be a useful marker to determine the requirement for adjunctive anti-cancer therapy, and the fact that the MIP-3α/CCR6/IL-17 axis should be investigated further as a potential novel therapeutic target." (PMID 25013520, 2014).
infection (109 papers, 2005 to 2026). The state of being infected such as from the introduction of a foreign agent such as serum, vaccine, antigenic substance or organism. "The CCR6 + T helper 17 subpopulation was particularly susceptible to such endothelial-cell-promoted infection." (PMID 37202790, 2023). "CXCR3+ TH1-like TFH cells, along with populations of CXCR5+CCR6+ unswitched classical and activated MBCs, were found among the most significant populations associated with increased risk of infection." (PMID 34128836, 2021). "CCR6+ cells associated with poor infection outcomes also expressed high levels of the Fc-like inhibitory receptor FcRL5, which has been found to be upregulated among MBCs with reduced capacity to differentiate into antibody-secreting cells." (PMID 34128836, 2021). "Phenotyping of mononuclear cells isolated from blood during the chronic phase of infection showed that Rh-α4β7 treatment was associated with an increase of CCR6+/CD95- CD4- cells compared to both control groups." (PMID 31083697, 2019). "The reduction in the levels of Treg-associated molecules, such as Foxp3, CCR5, CCR6, PD-L1 and Granzyme B, maintained even after week 10 post-infection, corroborates the beneficial effects of the early anti-CD25 treatment." (PMID 26512987, 2015). "While the overall recruitment of CD4 T cells into the skin was reduced in CCR6-deficient mice cytokine producing cells were more frequent indicating that the tendency towards inflammation was set early after infection in B6.CCR6−/− mice." (PMID 23028548, 2012). "CCR6 also plays a role in coronavirus disease (COVID-19), an infection caused by SARS-CoV-2 virus." (PMID 37092451, 2023). "Similarly, CXCR5+CCR6+ IgM+ classical and activated MBCs were associated with increased odds of symptomatic infection." (PMID 35475529, 2022). "Taken together, this might suggest that it is possible that the higher α4β7 expression observed on CCR6+ cells in black participants may contribute to possible increased risk of infection and disease progression in these individuals." (PMID 32841266, 2020). "Interestingly, we also found a small subpopulation of CD14+ monocytes with distinctly higher expression of previously unreported markers (CCR4, CXCR3, and CCR6) that also associated with the acute phase of infection." (PMID 30150281, 2018). "Moreover, heterogeneity in functional T helper cell phenotype similarly influences HIV entry and infection susceptibility with CCR6 expressing CD4+ T cells, notably Th17 and potentially Th22 cells, being preferential targets of HIV infection in the bloodstream and mucosa of the FRT." (PMID 39872519, 2024). "In a recent study we showed that C57BL/6 mice deficient in CCR6 exhibited enhanced footpad swelling and impaired T helper cell migration indicated by reduced recruitment of total T helper cells into the skin after infection and a reduced delayed type hypersensitivity reaction." (PMID 23028548, 2012). "Based on the fact that CCR6 is a receptor shared by Th17 and Treg cells, we hypothesized that CCR6 deficiency affects the establishment of functional Treg and Th17 cell immune responses leading to enhanced local inflammation during primary infection." (PMID 23028548, 2012). "Immunohistochemistry and flow cytometry revealed that CCL20-/- and CCR6-/- mice have impaired recruitment of T cells, especially CCR6+ T cells, to the site of infection." (PMID 40853122, 2025). "Tissue-resident molecules CXCR5 and CCR6 are expressed on the surface of MAIT cells, and stimulation by E. multilocularis infection causes MAIT cells migrate from the bloods to the site of infection." (PMID 38550591, 2024). "We observed that the infection significantly induced the expression of Il22 and Il17a in ILC3s, particularly in the CCR6+ cell compartments." (PMID 39013884, 2024).
infection (continued). "We found that CCR6 + T cells were preferentially infected, as was shown, but the infection was substantially increased and often to very high levels upon IEC stimulation, particularly with IEC +." (PMID 37202790, 2023). "We suspect the drop in CCR6 + cells in IEC stimulated infected T cell cultures was due to preferential cell death of CCR6 + cells after infection." (PMID 37202790, 2023). "One feature that was unique to acute infection cocultures was a strong increase in the relative abundance of CCR6-positive ILC subsets (e.g., 125-fold increase in C4)." (PMID 37000496, 2023). "The CCR6 + T cells stimulated by IEC + showed the highest levels of infection overall: as high as > 50%." (PMID 37202790, 2023). "During later stages, between 1-4 weeks of infection, a significant decline in blood γδ T cells and consistently increased GrB and CCR6 expression in both routes suggests induction of cytotoxic potential and increased homing to lungs during the recovery phase." (PMID 36526890, 2022). "Th17 cells participate in the dissemination of HIV following infection through their expression of mucosal migration receptors (CCR6, α4β7) and HIV co-receptors (CD4, α4β7, CCR5, and CXCR4) through different biological pathways." (PMID 35197986, 2022). "The absolute numbers of CCR6+NKp46- ILC3s were also reduced in Irf1–/– mice indicating that IRF-1 transcription controls cellularity of both ILC3 subsets during infection." (PMID 36175404, 2022). "While CCR6+ cells were significantly more abundant in response to infection, CCR6– atypical MBCs were significantly higher in healthy immune controls relative to infected individuals." (PMID 34128836, 2021). "CCR6+ Th17 cells are depleted in HIV-infected individuals and in pathogenic SIV rhesus macaque models of infection." (PMID 35055955, 2021). "Adjuvant β-defensins, a TLR3 agonist, acts as a strong immunostimulant that provokes an immune response by binding to its corresponding receptors, TLRs and CCR6, activating both immature dendritic cells and naïve T-cells at the infection location." (PMID 34452050, 2021). "Within the CD4+ T-cell compartment, memory CCR6+ Th17 cells were found to be preferentially infected very early following infection and harbor high levels of replication-competent HIV DNA compared to CCR6− T cells (40, 62, –, 64)." (PMID 32967958, 2020). "IECs respond to bacterial invasion by releasing IL-8 and CCL20, a pivotal step in the recruitment of granulocytes and CCR6+ lymphocytes (Th17 and Th1/17 cells) to the site of infection." (PMID 32752244, 2020). "Th17 cells, which express CCR6, and are overrepresented in the GALT, are also highly susceptible to infection." (PMID 32841266, 2020). "SIV studies in macaques suggest that CCR6+ CD4+ Th17 cells are preferential targets for early infection in the vaginal mucosa, possibly due to high levels of CCR5 expression." (PMID 29346424, 2018). "Preferential infection by HIV of CCR6+ TH17 cells in vitro has been described in a study which had cultured both TH1 and TH17 cells obtained from peripheral blood of healthy individuals in the presence of activated IL-1β and IL-23." (PMID 30004409, 2018). "Infection with Ccr6tg virus restored CCR6 expression in activated γδT17 cells, which regained the ability to migrate toward CCL20." (PMID 28580944, 2017). "The dynamics of the four CCR6+ subsets were studied in relationship with plasma viral load at different time-points post-infection, before and after ART initiation." (PMID 27553844, 2016). "We observed increased mRNA levels of the Th1/Th2/Th17-related major transcription factors Tbet, GATA3, and RORγC and diminished expression levels of Foxp3, CCR6 and PD-L1 after 2 weeks of infection." (PMID 26512987, 2015). "At 48 h after infection, Ccr6−/− mice had lower CSF-WBC counts, but increased brain volumes and an increased blood-brain barrier breakdown compared to infected WT mice." (PMID 24699535, 2014).